C9orf72 (C9orf72-SMCR8 complex subunit)
Diseases named in the same sentence as C9orf72 in open-access papers (continued):
Sharing a sentence is not in itself a finding about the gene and the disease.
frontotemporal dementia (continued). "Hexanucleotide repeat expansion (HRE) in the chromosome 9 open-reading frame 72 (C9orf72) gene is the most common genetic cause underpinning frontotemporal lobar degeneration (FTLD) and amyotrophic lateral sclerosis (ALS)." (PMID 33123074, 2020). "The C9orf72 hexanucletotide expansions are the primary genetic cause of familial amyotrophic lateral sclerosis and frontotemporal dementia." (PMID 30970637, 2019). "Such a recruitment defect would be consistent with a recent report of decreased 53BP1 foci at DSBs in models of C9orf72 repeat expansion, a common cause of amyotrophic lateral sclerosis and frontotemporal lobar degeneration." (PMID 31101070, 2019). "A G4C2 hexanucleotide repeat expansion in the noncoding region of C9orf72 is the major genetic cause of frontotemporal dementia and amyotrophic lateral sclerosis (c9FTD/ALS)." (PMID 30767771, 2019). "Hexanucleotide repeat expansions of variable size in C9orf72 are the most prevalent genetic cause of amyotrophic lateral sclerosis and frontotemporal dementia." (PMID 31843021, 2019). "A GGGGCC hexanucleotide repeat expansion within the C9orf72 gene is the most common genetic cause of both amyotrophic lateral sclerosis and frontotemporal dementia." (PMID 30604225, 2019). "Repeat expansions in the C9orf72 gene cause amyotrophic lateral sclerosis and frontotemporal dementia characterized by dipeptide-repeat protein (DPR) inclusions." (PMID 31673013, 2019). "A mutation in the C9orf72 gene is the most common cause of both amyotrophic lateral sclerosis and frontotemporal dementia, accounting for approximately 10% of all cases." (PMID 29113975, 2018). "C9orf72 is also linked to other neurodegenerative disorders such as frontotemporal dementia, parkinsonism, and Alzheimer's disease." (PMID 30159171, 2018). "Loss-of-function mutations in progranulin (GRN) and a non-coding (GGGGCC)n hexanucleotide repeat expansions in C9ORF72 are the two most common genetic causes of frontotemporal lobar degeneration with aggregates of TAR DNA binding protein 43 (FTLD-TDP)." (PMID 29855382, 2018). "Patients with ALS or frontotemporal lobar degeneration (FTLD) exhibit pathogenic C9orf72 G4C2 hexanucleotide repeat expansion." (PMID 29562705, 2018). "The G4C2-repeat expansion in C9orf72 is the most common known cause of amyotrophic lateral sclerosis and frontotemporal dementia." (PMID 30252044, 2018). "Hexanucleotide repeat expansion in C9orf72 is the most common genetic cause of frontotemporal dementia and amyotrophic lateral sclerosis, but the pathogenic mechanism of this mutation remains unresolved." (PMID 30075745, 2018). "Intronic GGGGCC repeat expansions in C9orf72 are the most common known cause of frontotemporal dementia (FTD) and amyotrophic lateral sclerosis (ALS), which are characterised by degeneration of cortical and motor neurons, respectively." (PMID 29113975, 2018). "The most common known genetic cause of ALS and frontotemporal dementia (FTD) is a hexanucleotide expansion within the first intron of the C9orf72 gene." (PMID 30454072, 2018). "A GGGGCC hexanucleotide repeat expansion in the C9orf72 gene is the most common genetic cause of amyotrophic lateral sclerosis and frontotemporal dementia." (PMID 29380049, 2018). "The repeat expansion in C9orf72 is the most common cause of amyotrophic lateral sclerosis and frontotemporal dementia." (PMID 28439722, 2017). "This massive hexanucleotide repeat expansion mutation in C9orf72, which has been linked to fALS, sALS, and frontotemporal dementia, has a single founder who is thought to have originated approximately 6300 years ago in Europe." (PMID 29216901, 2017). "Here we analyze RAN translation at G4C2 repeat expansions that cause C9orf72-associated amyotrophic lateral sclerosis and frontotemporal dementia (C9RAN) and at CGG repeats that cause fragile X-associated tremor/ataxia syndrome." (PMID 29222490, 2017).
frontotemporal dementia (continued). "Similar deleterious splice defects were previously reported for genes including DMD, C9orf72 and GR associated with muscular dystrophy, amyotrophic lateral sclerosis/frontotemporal dementia and small cell lung cancer respectively." (PMID 28187452, 2017). "An intronic GGGGCC expansion in C9orf72 is the most common known cause of both frontotemporal lobar degeneration (FTLD) and amyotrophic lateral sclerosis (ALS)." (PMID 28420437, 2017). "Hexanucleotide repeat expansion in the C9orf72 gene is a leading cause of frontotemporal lobar degeneration (FTLD) with amyotrophic lateral sclerosis (ALS)." (PMID 27193190, 2016). "Mutations in granulin (PGRN) and tau (MAPT), and hexanucleotide repeat expansions near the C9orf72 genes are the most prevalent genetic causes of frontotemporal lobar degeneration." (PMID 27100392, 2016). "The most common forms of amyotrophic lateral sclerosis and frontotemporal dementia are caused by a large GGGGCC repeat expansion in the first intron of the C9orf72 gene." (PMID 26916632, 2016). "A GGGGCC hexanucleotide repeat expansion in the C9orf72 gene is the most common genetic cause of amyotrophic lateral sclerosis and frontotemporal dementia (C9ALS/FTD)." (PMID 27334615, 2016). "Expanded repeats in C9orf72 is the most common genetic cause of frontotemporal dementia and amyotrophic lateral sclerosis." (PMID 26994292, 2016). "A GGGGCC repeat expansion in the C9orf72 gene was recently identified as a major cause of familial and sporadic amyotrophic lateral sclerosis and frontotemporal dementia." (PMID 25308964, 2015). "Recent studies have shown that expanded d(GGGGCC) repeats between exons 1a and 1b in C9ORF72 cause amyotrophic lateral sclerosis (ALS) associated with frontotemporal dementia." (PMID 26038313, 2015). "Expansion of a GGGGCC repeat located at C9orf72 is associated with familial amyotrophic lateral sclerosis and frontotemporal dementia." (PMID 26463209, 2015). "A massive expansion of a GGGGCC repeat upstream of the C9orf72 coding region is the most common known cause of amyotrophic lateral sclerosis and frontotemporal dementia." (PMID 26085200, 2015). "An expanded hexanucleotide repeat in the C9orf72 gene is the most common genetic cause of amyotrophic lateral sclerosis and frontotemporal dementia (C9ALS/FTD)." (PMID 25179228, 2015). "In this review we describe the various phenotypes, clinical and pathological, associated with expansion of C9orf72, which go beyond amyotrophic lateral sclerosis and frontotemporal dementia to include neurodegeneration more broadly." (PMID 25731823, 2015). "Mutations in C9ORF72 are an important cause of frontotemporal dementia (FTD) and motor neuron disease." (PMID 24521566, 2014). "An intronic G4C2 hexanucleotide repeat expansion in C9ORF72 is a major cause of amyotrophic lateral sclerosis and frontotemporal lobar degeneration." (PMID 24559645, 2014). "An expanded GGGGCC repeat in a non-coding region of the C9orf72 gene is a common cause of frontotemporal lobar degeneration (FTLD) and amyotrophic lateral sclerosis." (PMID 24170096, 2013). "An expanded hexanucleotide repeat in the C9orf72 gene is the most common genetic cause of frontotemporal dementia and amyotrophic lateral sclerosis (c9FTD/ALS)." (PMID 23818065, 2013). "Haploinsufficiency of C9orf72, the most frequently mutated gene in amyotrophic lateral sclerosis and frontotemporal dementia, has been linked to autophagy-lysosomal pathway defects, but the role of C9orf72 in microglia remains unclear." (PMID 42215790, 2026). "Cytoplasmic aggregates of the predominantly nuclear TAR DNA-binding protein 43 (TDP-43) are a pathological hallmark of amyotrophic lateral sclerosis (ALS) and frontotemporal dementia (FTD) cases caused by G4C2 hexanucleotide repeat expansions in C9orf72 (C9-ALS/FTD)." (PMID 40581653, 2025).
frontotemporal dementia (continued). "Also, the most common genetic cause of ALS and frontotemporal dementia is C9orf72 mutation, which can result in either pathology or in a combination of both." (PMID 40283201, 2025). "Mitochondrial dysfunction is a common feature of ALS/Fronto-temporal dementia (FTD) associated with G4C2 expansion in the C9orf72 gene; however, it remains unclear whether this condition is a cause or a consequence of the pathological process." (PMID 41155167, 2025). "Our specific aim was to evaluate glymphatic system abnormalities in presymptomatic and symptomatic individuals with pathogenic mutations within the MAPT, GRN and C9orf72 genes, to provide novel insight into the pathophysiology of genetic frontotemporal dementia." (PMID 39015769, 2024). "The most common hereditary form is associated with hexanucleotide repeat (GGGGCC) expansion located between the noncoding exons 1a and 1b of the C9ORF72 gene, also involved in the pathogenesis of frontotemporal dementia, with a pathogenic threshold of 61 repeats." (PMID 39596609, 2024). "It was in 2011 when the non-coding repeat expansion in the C9orf72 gene was discovered to be the most frequent cause of frontotemporal dementia (FTD) and amyotrophic lateral sclerosis (ALS); this gene and its derived protein, C9orf72, were utterly unknown." (PMID 38928395, 2024). "Another significant gene associated with frontotemporal lobar degeneration is C9orf72, mutations in which contribute to about 25% of familial cases and represent the most prevalent genetic cause of both frontotemporal dementia and amyotrophic lateral sclerosis." (PMID 38727281, 2024). "Nuclear depletion and cytoplasmic aggregation of the TAR DNA-binding protein 43 (TDP-43) is a pathological hallmark of amyotrophic lateral sclerosis (ALS) and frontotemporal dementia (FTD) patients caused by a hexanucleotide repeat expansion mutation in the C9ORF72 gene (C9-ALS and C9-FTD)." (PMID 37466726, 2023). "The presence of hexanucleotide GGGGCC (G4C2) repeat expansions in the C9orf72 gene represents the most common genetic cause of Frontotemporal Dementia (FTD) and Amyotrophic Lateral Sclerosis (ALS), two devastating neurodegenerative disorders commonly designated as c9FTD/ALS." (PMID 34349622, 2021). "To do this, we used positron emission tomography (PET) with the radioligand [11C]UCB‐J, which binds to synaptic vesicle protein 2A, in three asymptomatic carriers of C9orf72 mutations, a patient with symptomatic frontotemporal dementia, and 19 healthy controls." (PMID 34133849, 2021). "These expansions located in the 5′UTR (or first intron depending on the isoform) of C9ORF72 cause a dominant disorder characterized by frontotemporal dementia, amyotrophic lateral sclerosis, or the association of both at the individual level and/or within families (ALS/FTD, MIM #105550)." (PMID 38835438, 2021). "More than 40 REDs have been identified to date, including Huntington’s disease (HD), myotonic dystrophy type 1 (DM1), C9orf72-associated amyotrophic lateral sclerosis/frontotemporal dementia (ALS/FTD), and the FMR1 disorders, also known as the fragile X (FX)-related disorders (FXDs)." (PMID 34502075, 2021). "For example, several genes causing ALS and/or frontotemporal dementia (C9orf72, VCP, SQSTM1, OPTN, UBQLN2, GRN, CHMP2B) affect the autophagic machinery; and some Alzheimer’s Disease genes (APOE, TREM2, CD33, ABCA7) are preferentially or exclusively expressed in microglia." (PMID 33892821, 2021). "G-quadruplex motifs in the C9orf72 are responsible for the blockade of various functional proteins responsible for neurodegenerative diseases and are one of the main causes of Amyotrophic lateral sclerosis and frontotemporal dementia." (PMID 33101360, 2020).
frontotemporal dementia (continued). "As an example of the role in a human genetic disease, G-quadruplex structures of GGGGCC (G4C2) repeats form 800 to >4000 large hexanucleotide repeat expansions (HRE) in the C9orf72 gene implicated in the pathogenesis of C9orf72 amyotrophic lateral sclerosis and frontotemporal dementia (C9ALS/FTD)." (PMID 31200506, 2019). "Among the significant genes detected in females, a pathologic hexa-nucleotide repeat expansion in the C9orf72 gene has been linked to frontotemporal dementia and may contribute to AD pathogenesis." (PMID 30636644, 2019). "Here, we aimed to analyze the lipoprotein profile and inflammatory indicators, the high-sensitivity C-reactive peptide (hs-CRP) and glycoprotein acetyls (GlycA), in sporadic and C9orf72 repeat expansion-associated frontotemporal lobar degeneration (FTLD) patients." (PMID 31561355, 2019). "Moreover, volumetric imaging data from the genetic frontotemporal dementia initiative (GenFI) show an early affection of thalamus and cerebellum in C9orf72 mutation carriers compared to healthy controls (HC) as well as to GRN and MAPT mutation carriers." (PMID 29599716, 2018). "Recently, expansion of a GGGGCC hexanucleotide repeat in the gene C9orf72 has been identified as the most common genetic cause of frontotemporal dementia (FTD) and amyotrophic lateral sclerosis (ALS), two diseases that belong to the general class of disorders referred to as c9FTD/ALS." (PMID 30550541, 2018). "The CRISPR/Cas9 system has been successfully used to establish C9orf72-deficient mice since hexanucleotide repeat expansion in the C9orf72 gene has been recently discovered as a major cause of frontotemporal lobar degeneration (FTLD) with amyotrophic lateral sclerosis (ALS)." (PMID 29562705, 2018). "The RNA for ALS- and frontotemporal dementia-associated C9ORF72 gene is exported from nucleus via an unknown mechanism." (PMID 28677678, 2017). "In addition, deficits of body schema representation and self/non-self differentiation have been linked to somatic delusions and other neuropsychiatric disturbances in patients with frontotemporal dementia caused by pathogenic expansions in the C9orf72 gene." (PMID 27014028, 2016). "Here we demonstrate that GGGGCC and CAG microsatellite repeat RNAs associated with C9orf72 in amyotrophic lateral sclerosis/frontotemporal dementia and with polyglutamine diseases, respectively, localize to neuritic granules that undergo active transport into distal neuritic segments." (PMID 26650351, 2015). "There exists a genetic, clinical, and pathological overlap between ALS and frontotemporal dementia (FTD), whereby several genes (e.g., C9orf72, TARDBP, TBK1) have been associated with both conditions." (PMID 38986433, 2025). "Several variants, including C9orf72, are also associated with the pathologically related disorder frontotemporal dementia (FTD) and other neurological symptoms (Shatunov & Al‐Chalabi, 2021)." (PMID 38628040, 2025). "Neuropsychiatric symptoms (NPS) progress differently among individuals with autosomal dominant familial frontotemporal dementia (FTD) caused by genetic mutations in granulin (GRN+) or chromosome 9 open reading frame 72 (C9orf72+)." (PMID 40534487, 2025). "The expanded GGGGCC hexanucleotide repeat in intron 1 of the C9orf72 gene is the most common genetic cause of frontotemporal dementia (FTD) and ALS, accounting for ~40% of fALS cases and 5–7% of sALS cases." (PMID 38732027, 2024). "Hexanucleotide expansions in the gene C9ORF72 are the most common cause of the amyotrophic lateral sclerosis (ALS)/frontotemporal dementia (FTD) disease spectrum." (PMID 38658168, 2024). "The most common mutation associated with ALS and frontotemporal dementia (FTD) is the GGGGCC hexanucleotide repeat expansion (HRE) in the non-coding region of the C9orf72 gene." (PMID 38753768, 2024).
frontotemporal dementia (continued). "Hypermethylation of C9orf72 is linked to transcriptional repression in ALS/frontotemporal dementia (FTD) patients, potentially serving as a neuroprotective mechanism that mitigates molecular distortions related to hexanucleotide repeat expansions." (PMID 39376563, 2024). "Various family studies have shown a significant pathophysiological and clinical overlap between ALS and frontotemporal dementia (FTD), especially in cases related to variants in the C9ORF72, TARDBP, FUS, and VCP genes." (PMID 39596609, 2024). "For instance, a hexanucleotide repeat expansion in the intronic region of C9orf72 is the most common known cause of fALS and frontotemporal dementia (FTD)." (PMID 37083530, 2023). "Additionally, it has been proposed that repeat‐associated non‐ATG (RAN) translation of C9orf72 in the nucleus may contribute to human diseases, such as amyotrophic lateral sclerosis and frontotemporal dementia." (PMID 37063610, 2023). "More importantly, C9orf72 variants are the strongest determinant of comorbid frontotemporal dementia (FTD) with ALS (up to 88% of cases)." (PMID 37333000, 2023). "Heterozygous mutations in the GRN gene and hexanucleotide repeat expansions in C9orf72 are the two most common genetic causes of Frontotemporal Dementia (FTD) with TDP-43 protein inclusions." (PMID 36967384, 2023). "G4 structures of DNA sequences containing d[GGGGCC]n repeats found in the non-coding tract of the gene C9orf72 are linked to neurological disorders like frontotemporal dementia (FTD) and amyotrophic lateral sclerosis (ALS)." (PMID 38006038, 2023). "Hexanucleotide repeat expansion (HRE) within C9orf72 is the most common genetic cause of frontotemporal dementia (FTD)." (PMID 36446586, 2023). "A hexanucleotide repeat expansion (HRE) located in the 5′ UTR region of C9ORF72 gene is the most common genetic cause of familial frontotemporal dementia (FTD) and amyotrophic lateral sclerosis (ALS)." (PMID 37138765, 2023). "These cells originate from patients with amyotrophic lateral sclerosis (ALS) or frontotemporal dementia (FTD), both of which are associated with a C9orf72 repeat expansion)." (PMID 37759556, 2023). "The GGGGCC hexanucleotide repeat expansion (HRE) in the C9orf72 gene is the most common genetic cause of frontotemporal dementia (FTD) and amyotrophic lateral sclerosis (ALS)." (PMID 35625816, 2022). "The polymorphic hexanucleotide repeat expansion (HRE) in the C9ORF72 gene is the major genetic cause of amyotrophic lateral sclerosis/frontotemporal dementia (ALS/FTD)." (PMID 35568435, 2022). "The non-coding GGGGCC hexanucleotide repeat expansion (HRE) in C9orf72 gene is a dominant cause of frontotemporal dementia (FTD) and amyotrophic lateral sclerosis (ALS)." (PMID 35625816, 2022). "A GGGGCC repeat expansion in the C9orf72 gene is the most common cause of genetic frontotemporal dementia (FTD) and amyotrophic lateral sclerosis (ALS)." (PMID 35379698, 2022). "An intronic hexanucleotide (GGGGCC) expansion in the C9orf72 gene is the most common genetic cause of frontotemporal dementia (FTD) and amyotrophic lateral sclerosis (ALS)." (PMID 34744635, 2021). "Hexanucleotide repeat expansions (HREs) in C9orf72 are a major cause of frontotemporal dementia (FTD) and amyotrophic lateral sclerosis (ALS)." (PMID 33977144, 2021). "The most prevalent genetic cause of ALS and frontotemporal dementia (FTD) is a hexanucleotide repeat expansion (HRE) within the first intron of the C9orf72 gene." (PMID 34639106, 2021). "Expansions of a GGGGCC repeat in the C9orf72 gene are the most commonly identified genetic cause of ALS/frontotemporal dementia (C9-ALS/FTD)." (PMID 34631213, 2021). "A GGGGCC repeat expansion in C9orf72 is the most common genetic cause of frontotemporal dementia (FTD) and amyotrophic lateral sclerosis (ALS)." (PMID 31832771, 2020).